TSPAN5 (tetraspanin 5)
Description:
Part of TspanC8 subgroup, composed of 6 members that interact with the transmembrane metalloprotease ADAM10. This interaction is required for ADAM10 exit from the endoplasmic reticulum and for enzymatic maturation and trafficking to the cell surface as well as substrate specificity. Different TspanC8/ADAM10 complexes have distinct substrates. Promotes ADAM10-mediated cleavage of CD44. Seems to regulate VE-cadherin expression in endothelial cells probably through interaction with ADAM10, promoting leukocyte transmigration.
Synonyms: Tspan-5; TM4SF9; NET-4; NET4
Tractability: Antibody: UniProt places it where antibodies can reach, with high confidence; its Gene Ontology location is reachable by antibodies, with high confidence; UniProt predicts a signal peptide or a membrane-spanning region. PROTAC: ubiquitination databases record sites on it.
Gene: Protein-coding gene on chromosome 4 (98,470,365 to 98,658,690, reverse strand). Ensembl gene ENSG00000168785.
Subcellular location: Cell membrane
Subcellular location (Human Protein Atlas): Nucleoplasm; Plasma membrane
Pathways (Reactome):
Metabolism of proteins: Amyloid fiber formation
Gene Ontology:
Molecular function: enzyme binding; protein binding
Biological process: positive regulation of Notch signaling pathway; protein localization to plasma membrane; protein maturation; regulation of membrane protein ectodomain proteolysis
Cellular component: nucleoplasm; plasma membrane; endoplasmic reticulum lumen; membrane
Genetic constraint (gnomAD): Loss-of-function variants: 8 observed, 34.29 expected, observed/expected ratio (o/e) 0.23, 90% interval 0.14 to 0.42. The upper end of that interval is the gene's LOEUF score, 0.42, which puts it in group 1 of 6, group 1 being the genes least tolerant of losing a copy. Missense variants: 184 observed, 325.98 expected, observed/expected ratio (o/e) 0.56, 90% interval 0.5 to 0.64. Synonymous variants: 106 observed, 119.27 expected, observed/expected ratio (o/e) 0.89, 90% interval 0.76 to 1.04.
Homologues: Orthologues: chimpanzee TSPAN5 (100% identical), macaque TSPAN5 (100% identical), mouse Tspan5 (100% identical), rat Tspan5 (100% identical), dog TSPAN5 (99% identical), pig TSPAN5 (99% identical), guinea pig TSPAN5 (96% identical), rabbit TSPAN5 (92% identical). Paralogues in human: TSPAN17 (79% identical), TSPAN14 (58% identical), TSPAN33 (37% identical), CD82 (28% identical), TSPAN11 (27% identical), TSPAN15 (27% identical), TSPAN8 (27% identical), TSPAN4 (26% identical), TSPAN9 (26% identical), CD151 (26% identical), TSPAN18 (26% identical), TSPAN10 (25% identical), and 20 more.
Diseases named in the same sentence as TSPAN5 in open-access papers:
TSPAN5 is named in the same sentence as 24 diseases in open-access papers, as found by Europe PMC text mining. Sharing a sentence is not in itself a finding about the gene and the disease. The quoted sentences say what the papers report.
gastric cancer (4 papers, 2016 to 2023). A primary or metastatic malignant neoplasm involving the stomach. "Here we report that Tspan5 is significantly downregulated in gastric cancer (GC) and closely associated with clinicopathological features including tumour size and TNM stage." (PMID 27223087, 2016). "TSPAN5 has been shown to interact with ADAM10 and act as an oncogene in HCC and a tumor suppressor gene in gastric cancer." (PMID 37047447, 2023). "We also discuss several tetraspanins, including CD81, CD82, TSPAN5, TSPAN9, and TSPAN21 that suppress gastric cancer cell growth." (PMID 34222025, 2021). "In gastric cancer, the expression of TSPAN5 is significantly reduced and inversely correlated with tumor size and TNM stage, which indicates that TSPAN5 works as a tumor suppressor to inhibit the tumor proliferation, colony formation, and migration." (PMID 34222025, 2021). "Taken together, CD81, CD82, TSPAN5, TSPAN9, and TSPAN21 are regarded as tumor suppressors in gastric cancer to inhibit tumor cell growth and invasion, and enhance the sensitivity to apoptotic stress signals." (PMID 34222025, 2021). "In general, the expression of TSPAN8, CD151, TSPAN1, and TSPAN4 is increased in gastric cancer tissues and enhance the proliferation and invasion of gastric cancer cells, while CD81, CD82, TSPAN5, TSPAN9, and TSPAN21 are downregulated and suppress gastric cancer cell growth." (PMID 34222025, 2021). "According to the analysis of the Oncomine public database, we found that TSPAN5 is highly expressed in liver cancer and colon cancer, TSPAN26 is highly expressed in liver cancer and gastric cancer, and TSPAN9, TSPAN28, and TSPAN29 are highly expressed in gastric and colon cancer." (PMID 32694936, 2020).
colon cancer (3 papers, 2020 to 2023). "Consistent with our results, recent analyses of the Oncomine public database have shown that TSPAN5 is highly expressed in liver and colon cancer." (PMID 34771537, 2021). "TSPAN5 was not well-expressed in the cells other than the background in the normal tissues but was strongly expressed at the location of the cell membrane in the colon cancer tissues." (PMID 37047447, 2023).
hepatocellular carcinoma (3 papers, 2021 to 2023). A malignant tumor that arises from hepatocytes. "The first publication to support this prediction recently demonstrated that Tspan5 expression is associated with poor prognosis in hepatocellular carcinoma, one of the most common and lethal cancers." (PMID 34201472, 2021). "In hepatocellular carcinoma cell lines, Tspan5 over-expression promoted cell invasion in vitro, and tumor formation in the lung in a mouse model, while Tspan5 knockdown had the opposite effect." (PMID 34201472, 2021). "As discussed in the previous section, there is recent evidence that Tspan5 enhances Notch signaling to promote hepatocellular carcinoma, and a Tspan5 antibody has Notch inhibitory activity in a cell line model." (PMID 34201472, 2021). "In cancerous tumors, TSPAN5 plays a role in hepatocellular carcinoma (HCC) metastasis through epithelial-mesenchymal transition and regulates the growth of HCC in co-operation with other genes." (PMID 37047447, 2023).
alcohol use disorder (2 papers, 2020 to 2021). "In addition, a recent GWAS meta-analysis demonstrated that TSPAN5 SNPs were associated with alcohol use disorder (AUD) risk in an African–American population." (PMID 32753686, 2021). "TSPAN5 SNPs were also associated with alcohol consumption and alcohol use disorder (AUD) risk." (PMID 32753686, 2021). "Functional genomic studies demonstrated that ERICH3 was involved in clathrin-mediated vesicle formation and TSPAN5 was an ethanol-responsive gene that may be a marker for response to acamprosate pharmacotherapy of alcohol use disorder (AUD), a neuropsychiatric disorder highly co-morbid with MDD." (PMID 33510640, 2020).
breast carcinoma (2 papers, 2021 to 2025). "Similarly, several tetraspanins have been described to be enriched at the periphery of breast cancer cells and we have shown that expression of TSPAN5 in U2OS cells led to an enrichment of its partner ADAM10 at the cell periphery." (PMID 34445169, 2021).
liver cancer (2 papers, 2020 to 2021). An epithelial or non-epithelial malignant neoplasm that arises from the liver. "Moreover, investigation of the Kaplan–Meier Plotter dataset (Liver cancer RNA‐seq) showed that high expression of Tspan5 was significantly correlated with vascular invasion (P = 0.013), alcohol consumption (P = 0.0164) and hepatitis virus infection (P = 0.0012)." (PMID 33955149, 2021).
neuroblastoma (2 papers, 2020 to 2021). Neuroblastoma (NB) is the most common solid, extracranial childhood tumor. "Knock-down (KD) and overexpression (OE) of TSPAN5 in neuroblastoma cells significantly altered the expression of serotonin biosynthetic and metabolizing enzymes including TPH1, TPH2, DDC and MAOA, resulting in altered 5-HT concentrations in the cell culture media." (PMID 33510640, 2020). "Knocking down TSPAN5 and ERICH3 resulted in decreased 5-HT concentrations in neuroblastoma cell culture media and decreased expression of enzymes involved in 5-HT biosynthesis and metabolism." (PMID 33510640, 2020).
Alcoholism (1 paper, 2021). "We next set out to determine whether SNPs within TSPAN5 might be associated with the length of abstinence until the first drink of alcohol during 3 months of acamprosate treatment for AUD patients enrolled in the Mayo Clinic Center for the Individualized Treatment of Alcoholism clinical trial." (PMID 32753686, 2021).
Cirrhosis (1 paper, 2021). A chronic disorder of the liver in which liver tissue becomes scarred and is partially replaced by regenerative nodules and fibrotic tissue resulting in loss of liver function. "The prognosis of patients with cirrhosis correlates with the epigenetic modification of TSPAN5." (PMID 34540692, 2021).
Cognitive impairment (1 paper, 2024). Abnormal cognition is characterized by deficits in thinking, reasoning, or remembering. "MiR-322-5p could attenuate neuroinflammation and cognitive impairment in the CCH rat model through regulating negatively regulate tetraspanin 5 (TSPAN5)." (PMID 38231472, 2024).
colorectal cancer (1 paper, 2023). A primary or metastatic malignant neoplasm that affects the colon or rectum. "In this study, the overexpression of TSPAN5 was confirmed to be an independent prognostic marker that was associated with reduced overall survival in patients with colorectal cancer." (PMID 37047447, 2023). "Among the 200 tissues of the patients with colorectal cancer, TSPAN5 was highly expressed in 148 (74%), and 52 tissues showed low expression (26%)." (PMID 37047447, 2023). "We investigated the role of TSPAN5 in the functional aspects of cancer by suppressing the gene using small interfering RNA (siRNA), focusing on the colorectal cancer cell lines SW480 and SW620." (PMID 37047447, 2023). "In a previous study, we aimed to identify biomarkers related to the recurrence and metastasis of colorectal cancer, and tetraspanin 5 (TSPAN5) was selected as a candidate for the present study." (PMID 37047447, 2023). "In this study, we investigated the role of TSPAN5 in colorectal cancer recurrence and metastasis using colorectal cancer cell lines and tissues from patients with colorectal cancer." (PMID 37047447, 2023). "Furthermore, a previous study has described TSPAN5 overexpression in colorectal cancer and suggests the potential of TSPAN5 as a biomarker for colorectal cancer." (PMID 37047447, 2023). "Therefore, future studies should aim to assess the effects of TSPAN5 and other signal transduction systems in colorectal cancer and clarify the relationship between tumor formation and metastasis on the basis of the expression of TSPAN5 through animal experiments." (PMID 37047447, 2023).
gastric tumour (1 paper, 2016). "All such information might provide some clues to further understand how Tspan5 would regulate the cell cycle transition from G1-S phase in gastric tumour." (PMID 27223087, 2016).
Intellectual disability (1 paper, 2023). "Our data identify a novel function of TSPAN5 at the synapse and highlight AMPARs defective trafficking as a possible mechanism for intellectual disability symptoms in the AP4 deficiency syndrome." (PMID 36795458, 2023). "Importantly, we found that TSPAN5 exerts this function by interacting with AP4, a member of the adaptor protein complex family, which coding genes are mutated in a syndrome characterised by spastic paraplegia and intellectual disability." (PMID 36795458, 2023).
major depressive disorder (1 paper, 2021). An episode of depression lasting two or more weeks without an intervening episode of mania. "We previously reported that SNPs near TSPAN5 were associated with plasma serotonin (5-HT) concentrations which were themselves associated with selective serotonin reuptake inhibitor treatment outcomes in patients with major depressive disorder (MDD)." (PMID 32753686, 2021). "We previously reported that TSPAN5 eQTL SNPs on chromosome 4 were associated with variation in plasma serotonin (5-HT) concentrations which were themselves correlated with selective serotonin reuptake inhibitor treatment outcomes in patients with major depressive disorder (MDD)." (PMID 32753686, 2021).
Tinnitus (1 paper, 2022). Tinnitus is an auditory perception that can be described as the experience of sound, in the ear or in the head, in the absence of external acoustic stimulation. "In previous gene-wide analyses, it was shown that TSPAN5 was associated to tinnitus (uncorrected p = .00187) and that there is an association of ADAM10 with cisplatin-induced ototoxicity (uncorrected p = .0466)." (PMID 36699085, 2022).
tumor (10 papers, 2016 to 2025). "In this study, we demonstrate that the expression of Tspan5 is significantly associated with tumour invasive depth, vascular invasion, clinical stage and poor overall survival of HCC patients." (PMID 33955149, 2021). "We have demonstrated for the first time that Tspan5 is significantly upregulated and closely associated with tumour invasion, clinical stage and overall survival of HCC patients." (PMID 33955149, 2021). "Remarkably, the expression of Tspan5 is closely associated with some clinicopathological features including tumour size, invasive depth, lymph node metastasis and TNM stage and inversely correlated with overall survival of GC patients." (PMID 27223087, 2016). "Interestingly, decreased expression of Tspan5 was significantly associated with tumour size (P<0.001), tumour invasive depth (P<0.05), lymph node metastasis (P<0.05) and TNM stage (P<0.01)." (PMID 27223087, 2016). "Most importantly, TSPAN5 knockdown was also able to suppress HCC tumor growth in a CAM and in a xenograft model in vivo." (PMID 34771537, 2021). "We conclude that Tspan5 increases the cell migration and tumour metastasis by impelling EMT of HCC cells." (PMID 33955149, 2021). "It is therefore conceivable that a defect in exosome biosynthesis, nuclear content loading and SASP factor secretion contributes to the anti-tumor effects of TSPAN5 silencing observed in CAM tumors and HCC xenografts." (PMID 34771537, 2021). "To explore the specific role of Tspan5 in regulation of Notch signalling in HCC, we determined the expression of key players in Notch signalling after modulating the expression of Tspan5 in tumour cells." (PMID 33955149, 2021). "Increased expression of Tspan5 was frequently observed in tumours that are more invasive and in a later clinical stage." (PMID 33955149, 2021). "The therapeutic efficacy of a TSPAN5 knockdown strategy in vivo was then evaluated in a tumor xenograft mouse model." (PMID 34771537, 2021). "To understand the function of Tspan5 in tumour metastasis of HCC, we first examined the endogenous expression of Tspan5 in a variety of HCC cell lines by qRT‐PCR and western blotting." (PMID 33955149, 2021). "By activating Notch signalling, Tspan5 promoted epithelial–mesenchymal transition, actin skeleton rearrangement, tumour migration and metastasis of HCC, resulting in poor patient survival." (PMID 33955149, 2021). "Efficient TSPAN5 knockdown in vivo achieved by this PEI-based delivery platform for TSPAN5 siRNA reduced tumor growth by driving HCC cells into senescence." (PMID 34771537, 2021). "DBZ treatment not only abolished the wound healing and migration ability of tumour cells enhanced by Tspan5 but also further decreased the wound healing and migration capacity of all HCC cells." (PMID 33955149, 2021). "Analysis of the UALCAN dataset revealed Tspan5 transcripts were upregulated 1.1‐fold in tumour tissues of white, African‐American and Asian patients (P < 0.0001)." (PMID 33955149, 2021). "IHC staining of tumour sections confirmed the upregulation of Tspan5 in tumour cells compared to the control (P<0.001)." (PMID 27223087, 2016). "Tumour volume of Tspan5-overexpressing cells was about 9-fold less than that of control cells on day 20 (84.17±7.39 versus 746.40±57.15, P<0.001)." (PMID 27223087, 2016). "We then reconstituted cyclin D1 in Tspan5-overexpressing tumour cells by transfection with the pENTER-cyclin D1 expression vector." (PMID 27223087, 2016). "More importantly, upregulation of Tspan5 dramatically decreased the tumour growth in vivo by reducing tumour cell proliferation." (PMID 27223087, 2016). "Mechanistically, Tspan5 suppresses the tumour growth through regulating the cell cycle transition from G1-S phase by increasing the expression of p27 and p15 and decreasing the expression of cyclin D1, CDK4, pRB and E2F1." (PMID 27223087, 2016).